CNR2 (cannabinoid receptor 2)
Diseases named in the same sentence as CNR2 in open-access papers (continued):
Sharing a sentence is not in itself a finding about the gene and the disease.
neuroblastoma (6 papers, 2010 to 2022). Neuroblastoma (NB) is the most common solid, extracranial childhood tumor. "Our computational analysis identified CNR2-targeting compounds linked to multiple neuroblastoma risk signatures." (PMID 31900415, 2020). "A more exact mechanism of action of cannabinoid receptor 2 in high-risk neuroblastoma will be reserved for future work." (PMID 31900415, 2020). "However, judging from the absence of specific mutations or clear molecular patterns connected to the CNR2 biology in neuroblastoma, atypical targets like CNR2 would most likely be missed by common data mining strategies." (PMID 31900415, 2020). "Together, these data provided an independent set of data to support the potential of a CNR2 agonist against neuroblastoma, and encourage investigation to define MAPK8 (JNK1) inhibitors with improved toxicity profile as a future direction." (PMID 31900415, 2020). "We further found that neuroblastoma cells that were pre-treated with a CNR2 antagonist (SR144528) were protected against GW405833 (p = 0.014, Student’s t-test), while pre-treatment with a CNR1 antagonist (otenabant) had no protective effect." (PMID 31900415, 2020). "Using neuroblastoma xenograft models, we establish CNR2 and MAPK8 as promising candidates for the treatment of high-risk neuroblastoma." (PMID 31900415, 2020). "The finding that a CNR2 agonist GW405833 and a MAPK8 inhibitor AS601245 were active in neuroblastoma cells, motivated experiments to evaluate their on-target selectivity." (PMID 31900415, 2020). "Most of our predictions, including the CNR2 inhibitor GW405833, the UGCG inhibitor DL-PDMP, the TSPO antagonist PK11195, and the MAPK8/JNK inhibitor AS601245, downregulated the expression of genes induced during the cell cycle, implicating effects on neuroblastoma cell growth." (PMID 31900415, 2020). "In experiments on NB-PDX3 cells, two additional specific CNR2 agonists, JWH133 and HU308, reduced neuroblastoma cell viability, whereas the CNR1 agonist ACEA did not, nor did antagonists of either CNR1 or CNR2 suppress neuroblastoma cell growth." (PMID 31900415, 2020).
psychosis (6 papers, 2011 to 2024). "Literature about CNR2 genetic variability in psychosis is scarce, and it is mainly based on case–control association analyses about the risk of developing SZ." (PMID 39193030, 2024). "The genes encoding CB1R and CB2R (CNR1 and CNR2, respectively), have been proposed as candidate genes associated with psychosis and SZ." (PMID 39193030, 2024). "Despite the preliminary nature of the sample, our findings point towards the role of genetic variants at CNR1 and CNR2 genes in the severity of the disorganized symptoms of first-episode psychosis and modulating cognitive performance conditional to cannabis use." (PMID 39193030, 2024). "Regarding the CNR2 gene, our findings also suggest that the polymorphism rs25014131 and cannabis use are associated with brain activity changes in patients with a first-episode psychosis." (PMID 37108689, 2023). "Therefore, we have conducted a Gene × Environment study to assess the role of two common genetic variants at CNR1 (rs1049353) and CNR2 (rs2501431) genes and cannabis use on working memory brain function in a case-only sample of patients with a first-episode of psychosis." (PMID 37108689, 2023). "In individuals with psychosis, a decreased expression of the cannabinoid receptor 2 (CB2) and both endocannabinoids synthesizing enzymes (N-acyl phosphatidylethanolamine phospholipase and diacylglycerol lipase) have been found when compared to healthy controls." (PMID 39634076, 2024). "Thus, according to these data, it could be hypothesised that, in patients with psychotic disorders, CNR2 genetic variability influences CB2R activity and, finally, brain activity due to the regulation role of ECBS on other neural systems." (PMID 37108689, 2023). "However, our data indicate that the polymorphism of the CNR2 gene did not affect the risk of methamphetamine dependence and psychosis or the clinical phenotypes of methamphetamine psychosis in a Japanese population." (PMID 21886587, 2011).
alcohol dependence (5 papers, 2008 to 2022). Physical and psychological dependence on alcohol. "In a complementary manner, post-mortem studies analyzed CNR2 gene expression in the dorsolateral PFC and NAcc of patients with alcohol dependence criteria, revealing a reduction in both regions." (PMID 34827554, 2021). "Interestingly, our group recently carried out a postmortem study analyzing CNR2 in the dorsolateral prefrontal cortex (DLPFC) and NAcc of patients with alcohol dependence (unpublished data), showing an observed reduction in both regions." (PMID 35682586, 2022).
celiac disease (4 papers, 2013 to 2025). An autoimmune genetic disorder with an unknown pattern of inheritance that primarily affects the digestive tract. "More recently, in a cohort of children the Q63R variant of the CB2-encoding Cnr2 gene was shown to increase more than 6-fold the risk of celiac disease." (PMID 23620805, 2013).
cystitis (4 papers, 2018 to 2024). Inflammation of the urinary bladder. "CYP-induced cystitis did not significantly change the mRNA expression levels of Cnr1 or Cnr2; however, the protein expression levels of CB1R were markedly elevated, indicating an elevated ECS tone." (PMID 35647939, 2023).
Huntington disease (4 papers, 2012 to 2025). Huntington disease (HD) is a rare neurodegenerative disorder of the central nervous system characterized by unwanted choreatic movements, behavioral and psychiatric disturbances and dementia. "There is also evidence for the involvement of cannabinoid receptor 2 activation in microglia in neuroprotection against excitotoxicity in Huntington's disease." (PMID 22293457, 2012).
joint disease (4 papers, 2014 to 2023). "Similarly, the cannabinoid receptors Cb1 (Cnr1) and CB2 (Cnr2), which restrain sympathetic signaling, are implicated in age-related bone loss and joint disease." (PMID 33071963, 2020).
pancreatic cancer (4 papers, 2020 to 2025). "Cannabinoid receptor 2 and opioid growth factor receptor are highly expressed in pancreatic cancer tissue and their high expression improves OS, whereas high delta opioid receptor expression reduces OS." (PMID 37627066, 2023).
postmenopausal osteoporosis (4 papers, 2017 to 2022). Metabolic disorder associated with fractures of the femoral neck, vertebrae, and distal forearm. "For instance, it has been demonstrated that a missense variant (Gln63Arg) of CNR2, which was strongly associated with BMD in a population of postmenopausal osteoporosis patients, affects cannabinoid receptor type 2 (CB2) expression and activity." (PMID 33076329, 2020).
skin tumors (4 papers, 2019 to 2023). "The dysregulation of the endocannabinoid system, particularly cannabinoid receptor 2 (CB2), is implicated in skin cancer development, progression, and metastasis." (PMID 37175480, 2023).
adenomyosis (3 papers, 2019 to 2022). The growth of endometrial tissue inside the muscular wall of the uterine corpus. "In the present study, abnormal expression of spexin (SPX), cannabinoid receptor 2 (CNR2) and POU class 4 homeobox (POU4F3) may have been involved in sensory perception of pain in the myometrium of women with and without adenomyosis, relevant to dysmenorrhoea." (PMID 35773139, 2022).
amyloid (3 papers, 2015 to 2024). "Therefore, we first analyzed the Cnr2 expression levels in cortical microglia isolated from AppNL-G-F/NL-G-F mice, which exhibit cognitive decline with amyloid pathology and neuroinflammation." (PMID 39587077, 2024).
anxiety disorder (3 papers, 2017 to 2022). A category of psychiatric disorders which are characterized by anxious feelings or fear often accompanied by physical symptoms associated with anxiety. "Summary of the modulatory effects of cannabinoid receptor 2 (CB2r) on neuroinflammation in anxiety disorders." (PMID 35492718, 2022). "In the current study, we tested the association between polymorphisms of the CNR1, CNR2, and FAAH genes and response to CBT in children and adolescents with an anxiety disorder diagnosis." (PMID 27346075, 2017). "Given the potential role of the ECB system in fear extinction and the maintenance of extinction memories, this study investigated whether genetic variation in the CNR1, CNR2, and FAAH genes was associated with response to CBT in children and adolescents with an anxiety disorder." (PMID 27346075, 2017). "We investigated the relationship between variation in the CNR1, CNR2, and FAAH genes and change in primary anxiety disorder severity between pre‐ and post‐treatment and during the follow‐up period in the full sample and a subset with fear‐based anxiety disorder diagnoses." (PMID 27346075, 2017).
Autoimmunity (3 papers, 2019 to 2025). The occurrence of an immune reaction against the organism's own cells or tissues. "Interestingly, these increased T cells in the periphery did not cause autoimmunity in Cnr2-deficient mice, suggesting that the CNR2-mediated JAK-STAT signaling might have a limited effect on the negative selection of T cells in the thymus." (PMID 35383142, 2022).
Crohn disease (3 papers, 2019 to 2025). A gastrointestinal disorder characterized by chronic inflammation involving all layers of the intestinal wall, noncaseating granulomas affecting the intestinal wall and regional lymph nodes, and transmural fibrosis. "Our earlier findings demonstrated a significant association between the CNR2 rs35761398 polymorphism and susceptibility to pediatric IBD, particularly Crohn’s disease, as well as a more severe clinical phenotype in both UC and CD." (PMID 40332343, 2025). "This randomized, open-label phase 2a study investigated the safety/tolerability, pharmacokinetics, and efficacy of olorinab—a highly selective, peripherally acting, full agonist of the cannabinoid receptor 2—in patients with Crohn’s disease (CD) experiencing abdominal pain." (PMID 36777064, 2021).
promyelocytic leukemia (3 papers, 2013 to 2025). "CB2 is encoded by the CNR2 gene located on chromosome 1p36 and was first cloned in 1993 from human promyelocytic leukemia HL-60 cells." (PMID 35011388, 2021).
adenoma (2 papers, 2023 to 2025). A neoplasm arising from the epithelium. "Our results suggest that CB2 activation via OGP attenuates tumorigenesis and adenoma growth by modulating immune cells, corroborated by a significant association between CNR2 polymorphisms and monocytopoiesis in humans." (PMID 40307509, 2025).
arterial hypertension (2 papers, 2021 to 2024). "Cnr1 and Cnr2 expression was upregulated in both types of arteries and hypertension models, in comparison to their respective controls." (PMID 34832902, 2021).
chronic hepatitis (2 papers, 2014 to 2017). An active inflammatory process affecting the liver for more than six months. "We investigated the impact of the rs35761398 variant of the CNR2 gene on the clinical presentation of biopsy proven chronic hepatitis in 166 HIV/HCV coinfected patients." (PMID 28759568, 2017). "This is the first study to analyze the impact of the rs35761398 variant of the CNR2 gene leading to the substitution of GLN (Q) of codon 63 of the cannabinoid receptor 2 (CB2) with ARG (R) on the clinical presentation of chronic hepatitis in HIV/HCV coinfected patients." (PMID 28759568, 2017).
endometritis (2 papers, 2022 to 2024). An acute or chronic, usually bacterial infectious process affecting the endometrium. "One of the most interesting findings was the consistently higher expression of CNR2 in cows with endometritis at 7 weeks postpartum compared to 4 weeks." (PMID 39273135, 2024). "They reported that cows defined as subclinical endometritis/with endometrial inflammation exhibited increased mRNA expression of CNR2 and decreased expression of FAAH1 and NAAA, similar to our observations." (PMID 39273135, 2024). "CNR2 expression exhibited a time-dependent pattern in cows with endometritis." (PMID 39273135, 2024). "CNR2 showed a time-dependent pattern in endometritis, and PTGDS expression was elevated in clinical endometritis at 4 weeks postpartum." (PMID 39273135, 2024).
hearing loss (2 papers, 2021). "Similarly, a cardioprotective role for Cnr2 activation was described, but it remains to be demonstrated if Cnr2 can offer protection against all forms of hearing losses." (PMID 33958989, 2021).
peripheral nerve injury (2 papers, 2025). Injury to a peripheral nerve. "Here, we demonstrated that cannabinoid receptor 2 (CB2) plays a pivotal role in Schwann cells (SCs) by promoting the remyelination process following peripheral nerve injury (PNI)." (PMID 39776335, 2025). "Selective activation of cannabinoid receptor 2 (CB2) may also be considered as a therapeutic approach to promoting the remyelination process following peripheral nerve injury." (PMID 40940747, 2025).
acute liver failure (1 paper, 2024). Rapid deterioration of liver function causing encephalopathy and coagulopathy. "For example, activation of cannabinoid receptor 2 (CB2) has been shown to attenuate d-Galactosamine (GalN)/lipopolysaccharide (LPS)-induced acute liver failure by inducing an M1 to M2 shift in macrophages." (PMID 39582859, 2024).
acute pancreatitis (1 paper, 2014). An acute inflammatory process that leads to necrosis of the pancreatic parenchyma. "During acute pancreatitis, an upregulation especially of CB2 on apoptotic cells has been shown, and activation of cannabinoid receptor 2 attenuated the acute pancreatitis." (PMID 25403433, 2014).
bladder diseases (1 paper, 2021). "Future studies are needed to reveal the action of selective cannabinoid receptor 2 agonists and/or peripherally restricted synthetic cannabinoid receptor 1 agonists on bladder sensory neurons in animal models of bladder diseases." (PMID 34290614, 2021).
brain inflammation (1 paper, 2022). "Our results indicate the functional importance of the CNR2 gene loss for increased sensitivity to brain inflammation." (PMID 36475439, 2022).
emotional dysregulation (1 paper, 2024). "Alterations in Cnr2 gene expression might be related to emotional dysregulation, with anxiogenic and depressive behaviors and emotional hyperreactivity, as found in the behavioral evaluations." (PMID 39000559, 2024).
influenza (1 paper, 2013). An acute viral infection of the respiratory tract, occurring in isolated cases, in epidemics, or in pandemics; it is caused by serologically different strains of viruses (influenzaviruses) designated A, B, and C, has a 3-day incubation period, and usually lasts for 3 to 10 days. "In mice, genetic deletion of Cnr2 exacerbated contact allergic inflammation and influenza-induced excessive airway injury possibly via induction of pro-inflammatory and pro-remodeling mediators (IL-17, IL-13, TNF-α, GM-CSF)." (PMID 23844029, 2013).
mesothelioma (1 paper, 2022). A usually malignant and aggressive neoplasm of the mesothelium which is often associated with exposure to asbestos. "CNR2 was not expressed in any of the mesothelioma cell lines and was not included in the analyses." (PMID 35954477, 2022).
oral mucositis (1 paper, 2020). Inflammation of the mucous membranes of any of the structures in the mouth. "The role of cannabinoid receptor 2 (CB2) has not yet been investigated in oral mucositis." (PMID 32560286, 2020).
tumor (120 papers, 2006 to 2026). "Further, we used exomic analyses of UKBiobank patients to determine the relationship between CNR2 polymorphisms and tumor-associated myeloid cells in humans." (PMID 40307509, 2025). "Having found that Cnr2 deficiency enhanced the activities of tumor-specific T cells, we questioned whether these T cells could have superior therapeutic efficacy than wild-type T cells in tumor treatment." (PMID 35383142, 2022). "Although the developmental advantage might enhance the antitumor immunity in Cnr2-deficient mice, we found that shRNA knockdown of Cnr2 in wild-type OT-I T cells greatly enhanced their activities against tumor." (PMID 35383142, 2022). "Both PPARA and CNR2, potential target genes of β-elemene, have been shown to be involved in the tumour development process of NSCLC." (PMID 37980372, 2023). "Similar to Cnr2-deficient T cells, Cnr2 knockdown OT-I T cells significantly inhibited the growth of B16-OVA tumors and improved survival of tumor-bearing mice compared to the OT-I T cells transduced with LacZ shRNA." (PMID 35383142, 2022). "We further discovered that CNR2 mediated the suppressive effects of cannabinoids by inhibiting the function of tumor-specific T cells." (PMID 35383142, 2022). "Aberrant expression of components of the endocannabinoid system, especially CNR1 and CNR2, seems to be related to tumour growth and progression." (PMID 35008410, 2022). "Greenhough and colleagues reported that induction of CNR1 and CNR2 in colorectal cancer cells inhibits tumorigenic RAS/MAPK and PI3K/AKT signaling, while the loss of CNR1 in tumor samples from colon cancer patients correlated with tumor growth." (PMID 33746610, 2021). "CB2 (cannabinoid receptor 2) agonists have been shown to exert anti-tumor activities in different tumor types." (PMID 31053086, 2019). "Agonists selective for cannabinoid receptor 2 (CB2) are shown to inhibit tumor growth through inducing PI3K/AKT signaling, MAPK/ERK signaling and so on." (PMID 31053086, 2019). "Notably, downregulation of monoacylglycerol lipase (MGLL) in TAMs supports tumor growth by altering the catabolism of 2-arachidonoylglycerol (2-AG), which activates cannabinoid receptor-2 (CB-2) and promotes M2 macrophage polarization." (PMID 40092297, 2025). "Interestingly, MGLL in cancer cells promoted tumor progression by releasing special fatty acids whereas MGLL in TAMs suppressed cancer development by attenuating endogenous cannabinoid receptor 2 signaling." (PMID 37033945, 2023). "We further found that cannabinoids impaired the function of tumor-specific T cells through CNR2." (PMID 35383142, 2022). "Recent studies have found that reduced expression of monoacylglycerol lipase (MGLL) in TAMs facilitates tumor growth and that this molecule can catabolize 2-arachidonoylglycerol (2-AG), which promotes the cannabinoid receptor-2 (CB-2), leading to M2-type polarization of macrophages." (PMID 35454171, 2022). "Consistent with previous reports, we found that THC could inhibit the growth of tumor cells highly expressing CNR2." (PMID 35383142, 2022). "The tumour tissue shows increased Dagla and Cnr2 levels and reduced Cnr1 and Faah levels compared to the HC tissue; the AT1 tumours show increased Naaa levels and the MLL tumours show increased Napepld levels." (PMID 32286386, 2020). "For the targets for AEA and 2-AG, Cnr1 levels were lower and Cnr2 levels higher in the tumour tissue than in the HC tissue, and the Cnr2 levels higher in the AT1 tumour than the MLL tumour." (PMID 32286386, 2020). "Additionally, Cannabinoid receptor 2 (CNR2), a cannabinoid receptor, disrupts CD8+ T and NK cell activity in the TME and promotes tumor growth through the p38 MAPK pathway, making it a notable marker for HPV-positive HNSCC." (PMID 40486875, 2025).